CD4 (CD4 molecule)
Diseases named in the same sentence as CD4 in open-access papers (continued):
Sharing a sentence is not in itself a finding about the gene and the disease.
Sepsis (continued). "To functionally confirm the role of IL-9-producing CD4(+) T cells and IL-9 in the intestinal pathology, we used a rat sepsis model." (PMID 33941281, 2021). "The serum percentages of IL-9-producing CD4(+) T cells of the control group were significantly lower than that of the sepsis group (0.43%±0.03% vs. 1.58%±0.41%, P =0.021) or the sepsis+IL-9 group (0.43%±0.03% vs. 3.53%±0.90%, P < 0.001)." (PMID 33941281, 2021). "One study observed that in the CD4+ T cells of eight sepsis survivors, PD-1 receptor density was found to be downregulated as compared with healthy controls." (PMID 34945111, 2021). "In sepsis, an initial pro-inflammatory phase is characterized by increased cytokine levels and a CD4+ Th1 cell response." (PMID 33676566, 2021). "The serum percentages of IL-9-producing CD4(+) T cells of the sepsis+IL-9 group were significantly higher than that of the sepsis group (3.53%±0.90% vs. 1.58%±0.41%, P =0.001) or the sepsis+sh-IL-9 group (3.53%±0.90% vs. 0.80%±0.02%, P < 0.001)." (PMID 33941281, 2021). "The CD4+ T cells were co-cultured with naive Gr1+CD11b+ cells, which cannot suppress T cell, in the presence of exosomes purified from cultures of late sepsis Gr1+CD11b+ MDSCs in which Hotairm1 was knocked down first." (PMID 33335790, 2020). "It remains to be determined how sepsis affects the number and function of tissue-resident memory CD4 T cells." (PMID 32903436, 2020). "Our results demonstrate enhanced expression of IL‐38 in CD4+CD25+Tregs in a murine sepsis model and highlight the immune activity of CD4+CD25+Tregs." (PMID 31880383, 2020). "Altered functions and loss of other immune cell subsets likely plays a role in the remodeling of CD4 T cell subsets following sepsis." (PMID 32733454, 2020). "Strikingly, our data from CLP mice suggest that treatment with IL‐38 can notably improve the survival rate of septic mice and confirm that CD4+CD25+Tregs are required for the beneficial effects of IL‐38 in the development of sepsis." (PMID 31880383, 2020). "In the current study, we aimed to investigate the role of IL‐38 in mediated activity of CD4+CD25+ Tregs during sepsis in a murine model." (PMID 31880383, 2020). "These pro-inflammatory factors accelerate the apoptosis of lymphocytes, especially CD4+T cells, and dendritic cells, thereby aggravating sepsis immunosuppression." (PMID 32457606, 2020). "This study aimed to investigate the role of interleukin (IL)‐38, a newly described member of the IL‐1 cytokine family, in mediated immune response of CD4+CD25+ Tregs in sepsis." (PMID 31880383, 2020). "Sepsis led to decreased percentages of CD4+ lymphocytes (CD4+ in the gated CD3+ population) in blood." (PMID 32290120, 2020). "In our study we found that narciclasine treatment normalized the CD4/CD8 T lymphocyte ratio in neonatal rats with sepsis." (PMID 32076015, 2020). "Based on the literature, it is clear that sepsis disrupts both representation of and function of CD4 T cell subsets, including Th1, Th2, Th17, Tfh, and Treg subsets." (PMID 32733454, 2020). "There have been studies reporting a decreased absolute count and increased apoptosis of CD4 and CD8 lymphocytes during sepsis with different types of underlying infection." (PMID 33005098, 2020). "Clinical data show considerable reduction in number of circulating CD4 T cells (along with other lymphocyte populations) in sepsis patients of all ages and at the time of high pathogen burden." (PMID 32903436, 2020). "In accordance, polymicrobial sepsis in mice induces the upregulation of GRAIL in CD4+ T-cells, which limits their proliferation and effector functions and contributes to the T-cell immunoparalysis that is common in sepsis." (PMID 32582770, 2020). "Spleen CD4+ T cells were isolated from naive mice and cultured with naive Gr1+CD11b+ cells in the presence of exosomes derived from cultures of sham or sepsis Gr1+CD11b+ cells." (PMID 33335790, 2020).
Sepsis (continued). "As a result, we divided the experimental mice into three MSS groups (4–7, 8–10, and >10) to represent different degrees of sepsis and measured CD4+ T cell count and T-bet expression." (PMID 32431684, 2020). "CD4+ T cell count and T-bet expression had the same variation tendency in gene knockout mice with lethal Candida sepsis." (PMID 32431684, 2020). "In conclusion, sepsis-induced immunosuppression is initiated from a very early stage, represented by apoptosis of splenocytes, decreased CD4+ and CD8+ T cells, and a high expression level of PD-L1 on MDSCs." (PMID 32719675, 2020). "We tested the ability of the OVA323-specific memory CD4 T cells to provide protection against a secondary Lm-OVA infection after sepsis induction." (PMID 32903436, 2020). "Acute sepsis leads to decreased numbers of CD4+ and CD8+ T-cells due to apoptosis, followed by reversal to levels found in healthy individuals at six months after discharge." (PMID 33039713, 2020). "Sepsis affects most of the immune system functions, profound changes indeed impact leucocyte subsets including CD4+ T cells." (PMID 32949213, 2020). "CD4+ T cells derived from sepsis patients exhibited significantly increased expression of TRF1 and RAP1 compared to control samples (* p < 0.05)." (PMID 32825352, 2020). "This study investigated the effects of a single dose of arginine (Arg) administration at the beginning of sepsis on CD4+ T-cell regulation and liver inflammation in C57BL/6J mice." (PMID 32290120, 2020). "Findings of our study revealed that sepsis resulted in decreased CD4+ cell populations, lower Th1/Th2 ratios, and higher Th17/Treg ratios in the circulation and abdominal lymph nodes." (PMID 32290120, 2020). "A previous study also found that the GLN administration elicited a more balanced CD4 T cell polarization and downregulated programmed death-1 expression by T cells, thus preventing immunosuppression during sepsis." (PMID 33223959, 2020). "They found that when severe infection occurred, under the regulatory of Notch signaling pathway, CD4+ T cell count decreased and continued to decrease with the worsening of sepsis." (PMID 32431684, 2020). "We found that the proportion of CD45+F4/80+ macrophages was greatly increased, whereas CD45+CD11c+ dendritic cells (DCs) and CD3+CD4+ T helper cells were dramatically decreased in LPS-induced sepsis mice when compared to those of controls." (PMID 32457606, 2020). "Following sepsis, a number of CD4 T cell extrinsic factors have been found to suppress the activity of CD4 T cells, including the reduced APC function and TNF signaling." (PMID 32903436, 2020). "In a mouse model of sepsis, thymic output of CD4+ RTEs was reduced to approximately 11% in septic mice at up to eight days after the induction of sepsis; this output quickly recovered subsequently." (PMID 32825352, 2020). "Late sepsis Gr1+CD11b+ cells with Hotairm1 knockdown were co-cultured with CD4+ T cells isolated from spleens of naive mice." (PMID 33335790, 2020). "In this study, we intravenously administered 300 mg Arg/kg body weight (BW) after sepsis to investigate the influence of Arg on CD4+ T-cell regulation during sepsis." (PMID 32290120, 2020). "Our data collectively show CLP-induced sepsis alters the number and function of Ag-specific memory CD4 T cells, which contributes (in part) to the characteristic long-lasting immunoparalysis seen after sepsis." (PMID 32903436, 2020). "Apoptosis has been shown to be responsible for causing major depletion of immune cells, including CD4+ and CD8+ T cells, B cells and DCs in multiple organs from patients who died from sepsis." (PMID 33336293, 2020). "It is also important to note that while our study exclusively examined the in vivo function of memory CD4 T cells after sepsis, other publications have shown the environment is also a critical factor in sepsis-induced suppression of T cells." (PMID 32903436, 2020).
Sepsis (continued). "Levels of circRNA were significantly elevated in PBMCs of sepsis patients, with monocytes producing the highest amounts of circRNA relative to CD4+, CD8+ T cells, and B cells." (PMID 32660590, 2020). "Concerning subsets of CD4+ T cells, obesity with sepsis resulted in higher percentages of Th2 and Th17 cells at 12, 24, and 48 h and Treg cells at 24 and 48 h, while Th1-expressing cells had decreased by 48 h compared to the obesity sham group." (PMID 33223959, 2020). "Knockdown of Hotairm1 in late sepsis Gr1+CD11b+ MDSCs attenuated their suppressive effects on CD4+ T cells." (PMID 33335790, 2020). "The reduced number of MOG-specific CD4 T cell precursors seems to be a factor at a time proximal to sepsis induction." (PMID 33191915, 2020). "Third, despite their reduced ability to produce cytokines at day 30-post-sepsis, 2W1S-specific memory CD4 T cells were surprisingly able to expand upon Ag re-encounter 30 days after CLP to nearly sham levels." (PMID 32903436, 2020). "Since a cluster of differentiation 4-positive (CD4+) T helper (Th) cells are important lymphocyte subsets that influence innate and adaptive immunity during sepsis, the impacts of the parenteral GLN administration after peritonitis were investigated." (PMID 33223959, 2020). "CD4 T cells are among the immune cells significantly depleted during the acute stage of sepsis, but gradually recover during the immunosuppressive phase." (PMID 32903436, 2020). "Life-threatening situations such as major burns or sepsis relate to a significant decrease in CD4 cells, and patient survival goes along with lymphocyte count recovery." (PMID 33126723, 2020). "The results demonstrated that T cells exhausted in the late stage of sepsis, but apoptosis began very early especially for CD4+ T cells." (PMID 32719675, 2020). "The expression of catalytic TERT remained unchanged across the cell types and groups, whereas TERC expression was significantly upregulated in the CD4+ T cells of sepsis patients (* p < 0.05)." (PMID 32825352, 2020). "Understanding how sepsis impacts the CD4 T cell compartment is critical for informing efforts to develop treatments intended to restore immune system homeostasis following sepsis." (PMID 32733454, 2020). "Fewer studies have examined the effect of sepsis on Ag-experienced memory CD4 T cells compared to what has been done for memory CD8 T cells, driving our interest in the current set of experiments." (PMID 32903436, 2020). "The TREC content in the CD4+ T cells of patients with septic shock was significantly reduced compared to age- and sex-matched controls, indicating decreased RTEs in sepsis." (PMID 32825352, 2020). "Many defects in CD4 T cells have also been found, and due to their role in providing help to B cells and CD8 T cells, we will discuss the effects of sepsis on CD4 T cells in further detail in the following section." (PMID 32733454, 2020). "Lymphocyte populations are especially susceptible to apoptosis, and numbers of B cells and CD4 and CD8 T cells are markedly reduced following sepsis onset." (PMID 32733454, 2020). "When targeting to T cells, FACS analysis showed that surface expression of PD-1 on CD4+ T cells was upregulated from day 1 and keeping at a high level during sepsis." (PMID 32719675, 2020). "mTOR activity significantly increased after infection and further increased with aggravation of sepsis, which indicates that mTOR is involved in regulating CD4+ T cells in Candida sepsis." (PMID 32431684, 2020). "We found that the relative percentage of naïve T cells (CD4+CD45RA+) was similar in sepsis and controls." (PMID 32825352, 2020). "First, our data show CLP-induced sepsis results in a transient numerical reduction of 2W1S-specific memory CD4 T cells (current study), while 2W1S-specific naive CD4 T cells suffer from prolonged numerical reduction." (PMID 32903436, 2020).
Sepsis (continued). "Results showed that the coexistence of obesity and sepsis aggravated inflammation and dysregulation of CD4 T cells beyond that exerted by obesity alone." (PMID 33223959, 2020). "We found that CD4+ T cell count decreased in Candida-infected compared to uninfected mice, and the degree of decrease increased with aggravation of sepsis." (PMID 32431684, 2020). "The findings showed that sepsis resulted in decreases in blood and para-aortic lymph node CD4+ T-cell percentages, whereas percentages of interleukin (IL)-4- and IL-17-expressing CD4+ T cells were upregulated." (PMID 32290120, 2020). "Using conditional knock out mice, these studies revealed that deletion of 2B4 expressed specifically on CD4 T cells offers survival advantage following sepsis." (PMID 33613563, 2020). "In particular, sepsis can diminish the number of naive CD4 T cell precursors subsequently limiting the number of cells capable of responding to a given antigen." (PMID 33191915, 2020). "Dysfunction of CD4+ T-cell and imbalance of T helper (Th) and regulatory T (Treg) populations are characteristics of sepsis." (PMID 32290120, 2020). "As indirect evidence, increased CD4+/CD8+ T-lymphocyte ratio in death group was also a typical abnormality in sepsis." (PMID 32547323, 2020). "As antigen-specific CD4+ T cell responses play a significant role in the pathogenesis of MS, it is plausible that sepsis can modulate the development of MS and/or disease relapses." (PMID 33191915, 2020). "During lethal Candida sepsis, mice in which the mTOR signaling pathway was inhibited by T-cell-specific mTOR deletion had higher expression of T-bet and CD4+ T cell count than WT mice had." (PMID 32431684, 2020). "We established a lethal mice Candida sepsis model and used Murine Sepsis Score to group mice with different disease severity to establish the influence of T-bet expression on CD4+ T cell count in Candida sepsis." (PMID 32431684, 2020). "Flow cytometry analysis indicated that puerarin settled overall inflammation mainly by normalizing expanded macrophages with limited effects on dendritic cells and CD4+T cells in the circulation of sepsis mice." (PMID 32457606, 2020). "It was reported that HSYA effectively ameliorated sepsis-induced apoptosis of CD4+ T lymphocytes by its anti-inflammatory and anti-apoptotic effects." (PMID 32153410, 2020). "In the present study, after mice were infected, the CD4+ T cell count decreased significantly and decreased further with aggravation of sepsis, which meant that host immunity was impaired." (PMID 32431684, 2020). "This review will focus on our understanding of how CD4 T cells are impacted by sepsis and how changes within the CD4 T cell compartment affect overall immune fitness." (PMID 32733454, 2020). "Together, the experimental model systems used provided a unique means by which sepsis-induced immunoparalysis of memory CD4 T cells was evaluated." (PMID 32903436, 2020). "In order to assess the possible effect of IL‐38 on the immunosuppressive ability of CD4+CD25+ Tregs in sepsis, we stimulated cells with LPS followed by treatment with IL‐38 and anti–IL‐38 antibody." (PMID 31880383, 2020). "Similar reductions in functional capacity and protection were noted for the endogenous OVA323-specific memory CD4 T cell population in sepsis survivors upon Lm-OVA challenge." (PMID 32903436, 2020). "Although the impact of sepsis on autoimmunity is understudied, the known influences of sepsis on CD4 T cells and their environment provided a pivotal framework to begin interrogating this relationship." (PMID 33191915, 2020). "An animal study investigating the quantitative and qualitative recovery of T cells 3.5 months after sepsis found that despite a rapid recovery of T-lymphocytes, long-lasting impairments in the CD4+ T cells were prominent." (PMID 33336293, 2020).
Sepsis (continued). "To determine the effect of sepsis on multiple memory CD4 T cell populations generated following environmental pathogen/commensal exposure, we performed sham or CLP surgery on cohoused B6 mice age-matched to their SPF counterparts." (PMID 32903436, 2020). "Collectively, these data show pre-existing memory CD4 T cells experience a transient reduction in number during CLP-induced sepsis." (PMID 32903436, 2020). "We studied the potential role of CD4+CD25+Tregs in IL‐38–mediated protection against sepsis in vivo." (PMID 31880383, 2020). "Fungal Candida infected sepsis patients also demonstrate an increased PD-1 expression on circulating CD4 and CD8 T cells, and decreased CD28 expression." (PMID 33613563, 2020). "We observed a significantly decreased frequency of BM Tregs and an increased proportion of CD4+CD8+ effector T cells in BM during sepsis." (PMID 35006437, 2020). "In our previous report using sepsis model mice, we found an increased expression of IL-18 in CD4+ T cells of the spleen." (PMID 33344483, 2020). "In summary, the results of the present study suggest that Mdivi-1 reduces apoptosis in CD4+ T cells during sepsis." (PMID 31263382, 2019). "The decreased expression of the Th17 signature transcription factor in effector CD4+ T lymphocytes of patients with sepsis, but normal RORγt expression in naïve CD4+ T cells, suggests a failure of CD4+ Th17 differentiation in these patients." (PMID 31658288, 2019). "In sepsis, β2-adrenergic stimulation selectively inhibits CD4+ lymphocyte Th1 function and favours the Th2 responses that inhibit macrophage activation, T cell proliferation, and proinflammatory cytokine production." (PMID 31484576, 2019). "The percentage of CD3+CD4+ effector memory cells increased over time (p = 0.02) with CD4+ effector memory cells increasing two weeks after the onset of sepsis." (PMID 31658288, 2019). "Taken together, these findings indicate a potential mechanism by which disruption of HMGB1/PTEN axis activates β-catenin signaling and promotes TGF-β, which contributes to the induction of CD4+CD25+Foxp3+ Tregs during lung injury in sepsis." (PMID 31402909, 2019). "One of the most notable T cell defects induced by sepsis is the development of apoptosis, which destroys the CD4+ T cell population 151,152." (PMID 31611560, 2019). "Our results suggested that Mdivi-1 ameliorated apoptosis in CD4+ T cells by reestablishing mitochondrial fusion-fission balance and preventing the induction of endoplasmic reticulum stress in experimental sepsis." (PMID 31263382, 2019). "Balancing mitochondrial fusion-fission and preventing ER stress are two potential mechanisms involved in the protective effect of Mdivi-1 on CD4+ T cells in sepsis." (PMID 31263382, 2019). "We examined the long-term consequences of sepsis on CD4+ and CD8+ naive (CD62Lhi CD44-) and effector/memory (CD44+CD62Llo or +) T lymphocytes." (PMID 30730978, 2019). "We found that FoxP3 was more expressed by treatment with high (10 ng/mL) than low dose (10 pg/mL) of IL-1β, raising a possibility of IL-1β induced CD4 T-cell differentiation to regulatory T cells in sepsis." (PMID 31323786, 2019). "Similar results were observed with CD8+ T cell counts, except that TD cells were more prominent among CD8+ than CD4+ T lymphocytes, and were lower in patients with infection (p = 0.018) and sepsis (p = 0.001) compared to controls." (PMID 31658288, 2019). "IL-2 expression and release in CD4+ T cells was reduced under sepsis exposure, and this was reversed by inhibiting central HMGB1, especially at the dose of 10 μg BoxA." (PMID 30881224, 2019). "Taken together, our data are compatible with long lasting impairments in CD4+ T-cell responses after sepsis despite rapid recovery of T lymphocyte populations." (PMID 30730978, 2019). "Within the CD4+ T cell compartment, naïve cell counts were lower in sepsis patients than in controls (p = 0.0001) and lower with patients with infection than in those with sepsis (p<0.001)." (PMID 31658288, 2019).